NEFL (neurofilament light chain)
Diseases named in the same sentence as NEFL in open-access papers (continued):
Sharing a sentence is not in itself a finding about the gene and the disease.
COVID-19 (97 papers, 2020 to 2026). A disease caused by infection with severe acute respiratory syndrome coronavirus 2. "We aimed to evaluate the association between serum neurofilament light chain (NfL) and S100B biomarkers with the presence of neurological manifestations and functional prognosis in COVID-19 patients." (PMID 39779630, 2025). "Biomarkers of neurodegeneration in the cerebrospinal fluid (CSF), such as tau proteins, neurofilament light chain protein (NfL), and glial fibrillary acidic protein (GFAp), are increased in COVID-19 patients and associated both with neurological symptoms and disease severity." (PMID 33673697, 2021). "Similarly, COVID-19 has been associated with increased levels neuronal injury serum markers like neurofilament light chain (NfL), neuron-specific enolase while biomarkers like NfL, Glial fibrillary acidic protein, and tau were significantly increased in patients with fatal outcome." (PMID 37662953, 2023). "Various studies have demonstrated that the levels of biomarkers of neuronal injury, such as neurofilament light chain (NFL), correlate with encephalopathy, older age, severity of COVID-19 infection, and poor prognosis in hospitalized COVID-19 patients." (PMID 40563736, 2025). "Recently it has been demonstrated the relevance of plasma levels of neurofilament light chain (pNfL), as a biomarker of early involvement of the CNS in COVID-19." (PMID 38678084, 2024). "Some common biomarkers that can be considered for neuronal injury during COVID-19 and AD include p-tau, neurofilament light chain protein (NFL), and glial fibrillary acidic protein (GFAp) microvascular injury." (PMID 38535583, 2024). "We conducted an observational study to assess safety of COVID-19 vaccines in MS patients, not only at a clinical level, but also at molecular level by comparing serum neurofilament light chain levels before and after vaccination." (PMID 39238642, 2024). "Acute coronavirus disease 2019 (COVID-19) is paralleled by a rise in the peripheral levels of neurofilament light chain (NfL), suggesting early nervous system damage." (PMID 39125829, 2024). "Other studies on the correlation of neurofilament light chain levels and COVID-19, and in general, studies with patients treated on ICU should consider this important link." (PMID 37770938, 2023). "In this study, authors have shown increased plasma neuro–axonal damage specific biomarker neurofilament light chain (NfL) levels in COVID-19 patients, specifically those with ARDS." (PMID 37243203, 2023). "This meta-analysis assessed the relationship between glial fibrillary acidic protein (GFAP) and neurofilament light chain (NfL) levels in the blood and neurological injury in COVID-19 patients." (PMID 37958721, 2023). "Their research team discovered notable increases in serum T-tau, P-tau 181, glial fibrillary acidic protein (GFAP), and neurofilament light chain (NfL) levels in individuals with COVID-19-induced encephalopathy." (PMID 38187359, 2023). "Another study on 100 COVID-19 patients at 6 months confirmed that GFAP levels as well as initial increases in neurofilament light chain (NfL) tended to normalise over time." (PMID 37657964, 2023). "CSF levels of neurofilament light chain, Ubiquitin carboxyl-terminal hydrolase L1 and Tau were similar in patients with persistent headache in post-COVID-19 compared to acute COVID-19 patients and all control groups." (PMID 37759276, 2023). "In critically ill COVID-19 patients, this evidence is suggested by the increased level of serum neurofilament light chain (sNfL) which is a clue of direct neuronal injury." (PMID 35453524, 2022). "Hospitalized patients with COVID-19 show increased serum concentrations of neurofilament light chain that correlate with worse clinical outcomes." (PMID 34131052, 2021). "A small Swedish clinical trial demonstrated that CSF of COVID-19 patients with neurological symptoms showed an elevated neurofilament light chain protein (NfL) level that resembles axon injury." (PMID 34484241, 2021).
COVID-19 (continued). "Elevated levels of neurofilament light chain in COVID-19 patients with ongoing neurocognitive symptoms post-COVID suggest that neuroaxonal damage may be present." (PMID 39220656, 2024). "Studies on COVID-19 patients have highlighted critical brain injury biomarkers, such as neurofilament light chain (NfL), glial fibrillary acidic protein (GFAP), and matrix metalloproteinase-9 (MMP-9), which are essential in understanding the extent of neural damage." (PMID 39064167, 2024). "Recent studies have also related serum biomarkers to COVID-19 severity and mortality, including neurofilament light chain (NfL), glial fibrillary acidic protein (GFAp), total TAU (Microtubule-Associated Protein Tau, MAPT), and Ubiquitin carboxy-terminal hydrolase L1 (UCH-L1)." (PMID 36362378, 2022). "Levels of neurofilament light chain and glial fibrillary astrocytic protein, i.e. markers of neuronal damage and reactive astrogliosis, were lower in blood from patients with persistent Post-COVID-19 headache compared to patients with severe COVID-19." (PMID 36310154, 2022). "Here, we evaluated whether serum neurofilament light chain (NFL), a neuroaxonal injury marker, could predict the extent of neuronal damage in a cohort of 142 hospitalized patients with COVID-19." (PMID 34131052, 2021). "Indeed, evidence suggests a direct neuronal injury, as shown by increased serum neurofilament light chain (sNfL) levels, in critically ill COVID-19 patients compared to critically ill non-COVID-19 patients." (PMID 33709220, 2021). "Moreover, the levels of specific peripheral biomarkers that are routinely used in clinical practice for AD diagnosis—such as total tau protein in association with IL-6, Neurofilament Light Chain (NFL) and Glial Fibrillary Acidic Protein (GFAP)—are elevated in the CSF and serum of COVID-19 patients." (PMID 37998336, 2023). "Neurofilament light chain (NfL) and glial fibrillary acidic protein (GFAP) are increased in acute COVID-19." (PMID 38438479, 2024). "Recent studies have shown increased levels of neuroinflammatory proteins and neural injury markers such as glial fibrillary acidic protein (GFAP), neurofilament light chain (NFL), and Tau in patients with COVID-19 in plasma or cerebrospinal fluid (CSF)." (PMID 35937088, 2022). "Another study showed elevated plasma levels of neurofilament light chain protein (NfL), a marker of neuronal injury and glial fibrillary acidic protein (GFAP), a marker of astroglial injury in COVID-19 patients, suggestive of direct CNS damage." (PMID 34646224, 2021). "SARS-CoV2 infection was reported to lead to elevated plasma levels of neurofilament light chain protein (NfL) and glial fibrillary acidic protein (GFAP) two markers usually indicative of CNS injury in patients with COVID-19." (PMID 33953960, 2021). "Analysis of markers indicating CNS lesions revealed elevated levels of neurofilament light chain (NfL) and glial fibrillary acidic protein (GFAP) in plasma of patients with moderate to severe COVID-19." (PMID 34942956, 2021). "Two plasma biomarkers of CNS injury, neurofilament light-chain protein (NfL, a marker of neuroaxonal injury) and glial fibrillary acidic protein (GFAP, a marker of astrocytic activation/injury), were increased in severe COVID-19 patients." (PMID 34593760, 2021). "For example, neurofilament light chain was not measured, although neurofilament light chain elevation in the acute phase of COVID-19 has been demonstrated, depicting it as a marker of interest for further evaluation in PCS." (PMID 37999770, 2024). "Markers of brain injury, including neurofilament light chain (NFL), indicative of axonal damage, and glial fibrillary acidic protein (GFAP), a marker of astrocyte reactivity, were shown to be elevated in serum of COVID-19 patients." (PMID 39720706, 2024).
COVID-19 (continued). "NeuroCOVID is also characterized by neurodegeneration and elevations in the neurofilament light chain (NFL) in the blood, which may represent a useful tool to investigate the disease severity in COVID-19-affected individuals." (PMID 36831321, 2023). "In fact, neuroaxonal injury is often subclinical, and surrogate markers such as neurofilament light chain protein (NfL) are key to its detection; though significantly correlating with clinical severity, NfL also appears to be elevated in COVID-19 cases without prominent CNS manifestations." (PMID 38375477, 2024). "Neurofilament light chain (NfL), glial fibrillary acidic protein (GFAP), and total-tau protein (tau) are novel blood biomarkers of neurological injury, and may be used to predict outcomes in critical COVID-19." (PMID 37768470, 2023). "Neurofilament light chain (NfL) is specific for neuronal damage, the increased plasma NfL levels in patients without neurological symptoms suggest the presence of subclinical CNS involvement in patients with a history of COVID-19, especially in those with the most severe forms of the disease." (PMID 37257164, 2023). "Background and Methods: Severe COVID-19 is known to induce neurological damage (NeuroCOVID), mostly in aged individuals, by affecting brain-derived neurotrophic factor (BDNF), matrix metalloproteinases (MMP) 2 and 9 and the neurofilament light chain (NFL) pathways." (PMID 36831321, 2023).
brain injury (84 papers, 2012 to 2026). Acute and chronic (see also brain INJURIES, CHRONIC) injuries to the brain, including the cerebral hemispheres, CEREBELLUM, and brain STEM. "A 2021 study found that n-3 supplementation (2880 mg, 560 mg + 2000 mg) in American football players attenuated increases in neurofilament light chain (Nf-L) levels, a marker of neural damage, suggesting that n-3 may exhibit protective effects against sports-related brain injury." (PMID 39861437, 2025). "EV levels of neurofilament light chain (NfL), a neurofilament protein and marker of axonal injury or degeneration, and glial fibrillary acidic protein (GFAP), a filament protein found in astrocytes, were higher in patients with diffuse brain injury than those with focal injury." (PMID 36636744, 2022).
diabetes (84 papers, 2019 to 2026). "Unsurprisingly, prevalent diabetes and high HbA1c levels were both linked with increased neuroaxonal damage quantified by neurofilament light chain (NfL) levels." (PMID 37169935, 2023). "In the past, there has been a clear conclusion regarding the sole impact of serum neurofilament light chain (sNfL) levels or type 2 diabetes mellitus (DM) on the risk of death." (PMID 39256785, 2024). "In relation to biomarkers, PD patients with diabetes have higher neurofilament light chain and Tau level but lower Amyloid beta level." (PMID 39847072, 2025). "However, high levels of neurofilament light chain were a significant predictor of poor diabetes control (r = 0.41; p = 0.02) and kidney damage (r = 0.45; p = 0.01)." (PMID 38971890, 2024). "Serum levels of neurofilament light chain could not reflect current pain severity but was strongly associated with kidney dysfunction and poor diabetes control." (PMID 38971890, 2024).
depression (59 papers, 2012 to 2026). "At baseline, we assayed plasma phosphorylated tau 217 (p-tau217) and neurofilament light chain (NfL), and assessed depressive symptoms using the Center for Epidemiologic Studies Depression scale." (PMID 41556110, 2026). "Evidence suggests that major depressive disorder is related to neuroaxonal injury and that neurofilament light chain (NfL) is a biomarker of neuroaxonal injury." (PMID 34637515, 2022). "The search strategy was performed using specific search terms (i.e., [NfL OR neurofilament light chain] AND [human] AND [psychiatry OR psychiatric OR depression OR depressive OR schizophrenia OR psychosis OR substance use disorder OR anorexia OR bipolar disorder])." (PMID 38503931, 2024). "ACTB, CKB, NEFL, INA and GFAP had link to both schizophrenia and depression, while CTSD, HSPA8, NEFM and TUBA1A had link to schizophrenia." (PMID 23272063, 2012). "Understanding the relationship between the plasma neurofilament light chain (NfL) and brain-derived neurotrophic factor (BDNF) may help us to better understand the mechanisms of depression." (PMID 38255209, 2024).
Atrophy (54 papers, 2013 to 2026). Any weakening or degeneration, especially through lack of use. "N status can be evaluated by hypometabolism patterns of [18F]-fluorodeoxyglucose (FDG) PET, atrophy on structural MRI (magnetic resonance imaging), and neurofilament light chain (Nfl) in fluid assays (CSF or plasma)." (PMID 41440067, 2025). "Blood neurofilament light chain (NFL) is a neuronal damage marker that has been linked to relapses, deterioration of the EDSS score, lesions on MRI images, and atrophy of both the brain and spinal cord in MS patients." (PMID 37808700, 2024). "Other recommendations include using validated visual atrophy rating scales and volumetric analyses of brain regions on MRI, 18F-fluorodeoxyglucose PET, neurofilament light chain in serum or cerebrospinal fluid (CSF), and screening for C9orf72 mutation in patients with prevalent psychiatric symptoms." (PMID 34552551, 2021).
neuropathy (50 papers, 2014 to 2026). A disorder affecting the nervous system that manifests with pain, tingling, numbness, and/or muscle weakness. "Therefore, the NEFL missense mutations seem to cause neuropathy through accumulation of neurofilaments in the soma, which reduces their amount and functionality in axons." (PMID 35237613, 2021). "In particular, we will focus on neurofilament light chain (NfL) in blood as a response biomarker of disease activity in different neuropathies." (PMID 34661878, 2021). "A common pathological mechanism of axonal neurofilament dysregulation is likely to be responsible for neuropathy in the case of both dominant and recessive NEFL mutations as well as in other disorders caused by NFL aggregation." (PMID 35237613, 2021). "Similarly, in AL amyloidosis, neurofilament light chain (NfL) levels correlate with the severity of neuropathy, autonomic decline, and poor survival, serving as a potential biomarker." (PMID 41464866, 2025). "In A-ATTRv, severity of neuropathy correlates with serum neurofilament light chain (sNFL) levels." (PMID 38698025, 2024). "We previously demonstrated that a neuropathy-causing homozygous nonsense mutation in NEFL led to the absence of NFL in patient-specific neurons." (PMID 35237613, 2021). "Hearing loss could develop simultaneously with neuropathy, in some patients with pathogenic variants in PRPS1 (n = 1), NEFL (n = 2), MPZ (n = 1), TRPV4 (n = 1); or at a distance in some cases of variants in SH3TC2 (n = 2) and ABHD12 (n = 1)." (PMID 31393079, 2019).
Hypertension (49 papers, 2018 to 2026). The presence of chronic increased pressure in the systemic arterial system. "In a sample of healthy individuals over 60 years, kidney function was found to negatively correlate with neurofilament light chain (NfL), partially explaining the link between hypertension and a poorer prognosis after ALS diagnosis." (PMID 38878106, 2024). "This cross-sectional study examined associations between circulating fatty acid profiles, neurodegeneration (assessed by serum neurofilament light chain, NfL), cognitive function, and hypertension in 1,677 U.S. adults from the National Health and Nutrition Examination Survey (NHANES) 2013–2014." (PMID 40606500, 2025).
Huntington disease (48 papers, 2009 to 2025). Huntington disease (HD) is a rare neurodegenerative disorder of the central nervous system characterized by unwanted choreatic movements, behavioral and psychiatric disturbances and dementia. "The concentrations of neurofilament light chain (NfL) in cerebrospinal fluid (CSF) and plasma have become key biomarkers of many neurodegenerative diseases, including Huntington's Disease (HD)." (PMID 39022122, 2024). "Recent publications conclude that quantifications of neurofilament light chain (NFL) in biofluids can be used to sensitively estimate neurodegeneration in rodent models of Creutzfeldt–Jakob disease, Huntington’s disease, and tauopathies, as well as in genetic models of synucleinopathies." (PMID 38334646, 2024). "The BAD, NEFH, NEFL and DERL1 genes are also involved in Huntington’s disease pathways." (PMID 23782433, 2013).
ischemic stroke (47 papers, 2020 to 2026). A stroke disorder caused by obstruction of blood flow to the brain, due to thrombotic (local blood clot formation) or embolic (due to a blood clot or other material traveling from another site) event. "We profiled plasma levels of 91 neurology-related proteins (Olink Neurology panel) and serum Neurofilament light chain (NfL) levels in 205 cases in the Sahlgrenska Academy Study on Ischemic Stroke." (PMID 40316737, 2025). "This study investigated the impact of obstructive sleep apnea (OSA) on cognitive outcomes after ischemic stroke (IS) and the predictive value of plasma neurofilament light chain (pNFL) levels." (PMID 40546265, 2025). "Keywords such as ischemic stroke, biomarkers, neurofilament light chain (NfL), bilirubin, thioredoxin, netrin-1, omentin-1, circular RNA, diffusion tensor imaging, EEG, TMS, motor recovery, and machine learning." (PMID 41303115, 2025). "Furthermore, future studies should explore the role of serum neurofilament light chain in the ischemic lacunar stroke group compared to the non-lacunar ischemic stroke group." (PMID 40304765, 2025).
amyloid (46 papers, 2019 to 2026). "To further explore if amyloid pathology caused elevation of biomarkers of neurodegeneration in AppSAA KI mice, we measured total tau and neurofilament light chain (Nf-L) in CSF." (PMID 35690868, 2022). "Background/Objectives: Serum neurofilament light chain (sNfL) is a biomarker for peripheral neuropathy as sNfL correlates with polyneuropathy severity in hereditary transthyretin (ATTRv) amyloidosis." (PMID 41827277, 2026).
tauopathy (40 papers, 2012 to 2026). Neurodegenerative disorders involving deposition of abnormal tau protein isoforms (tau proteins) in neurons and glial cells in the brain. "More recently, new biomarkers are increasingly being validated, including blood-based biomarkers such as pTau 217 and pTau213 for tauopathy, neurofilament light chain (NfL) for neuronal injury, and glial fibrillary acidic protein (GFAP) for neuroinflammation." (PMID 41342674, 2025). "To further interrogate CNS damage caused by tauopathy, or potentially caused by the observed sex-dependent PLX exposure, we also evaluated the plasma levels of neurofilament light chain (NfL)." (PMID 36624100, 2023). "Similarly, in FTD, key proteins implicated in tauopathies and neurofilament dynamics were identified: MAPT (β = −0.32, P = 3.1 × 10−5) and NEFL (β = 0.28, P = 2.3 × 10−4)." (PMID 40665052, 2025). "In contrast, other plasma biomarkers of AD pathology, including tauopathy (total tau) and neurodegeneration (neurofilament light chain [NfL]), have shown more consistent findings, with elevations seen among individuals with DS who have been diagnosed with AD (DS-AD)." (PMID 34439728, 2021). "The neurofilament light chain (NfL), phosphorylated neurofilament heavy chain (pNfH) and chitinase-3-like protein 1 (YLK-40) were described as statistically significant CSF differentiating biomarkers to discriminate tauopathies and synucleinopathies." (PMID 36553028, 2022).